LRP1 (LDL receptor related protein 1)
Diseases named in the same sentence as LRP1 in open-access papers (continued):
Sharing a sentence is not in itself a finding about the gene and the disease.
tumor (continued). "Apart from the tumor cells, LRP-1 immunoreactivity has also been reported in the vascular endothelial cells, similar to the index study indicating the possible role of LRP in neovascularization in GBM." (PMID 36267880, 2022). "We analyzed the expression of LRP1 in tumor tissues of SKCM patients (T) and healthy controls (N) using TIMER." (PMID 36612285, 2022). "In contrast, LRP-1 was shown to activate promigratory signals in various cell types, including tumor cells." (PMID 36052226, 2022). "In accordance with the altered distribution of talin observed by immunocytochemistry, we detected an accumulation of both native and cleaved forms of talin in LRP-1-silenced tumor cells." (PMID 36052226, 2022). "Independent of the EGFR signalling, the second parallel “eHsp90α > LRP-1 autocrine loop” to promote tumour cell migration has been clearly established by previous studies." (PMID 35835845, 2022). "MDK can combine with its receptor LRP1, which is beneficial to tumor-infiltrating macrophages, promoting myeloid inhibitory cell differentiation (MDSCs)." (PMID 35935940, 2022). "Following LRP-1 repression, we showed that increased calpain activity coincided with an overspread morphology of tumor cells that accumulated more peripheral talin-positive complexes." (PMID 36052226, 2022). "Herein we show that LRP-1 orchestrates two parallel cell surface signalling pathways to support the full constitutive tumour cell migration." (PMID 35835845, 2022). "Given LRP-1 is highly expressed within such tumor microenvironment provides the rational for An2 conjugates to overcome the BBTB." (PMID 36430705, 2022). "We evidenced an increase of 34,5% of the capacity of LRP-1-silenced cells to degrade calpain substrate II in vitro, as compared to control tumor cells." (PMID 36052226, 2022). "Results of the quantitation demonstrated that the LRP-1 plays a critical role in self-supported motility of the tumour cells." (PMID 35835845, 2022). "Owing to its capacity to control the pericellular levels of various growth factors and proteases, LRP-1 plays a crucial role in tumor progression." (PMID 36106114, 2022). "We found that LGALS9_CD44, MIF_TNFRSF14, CD47_SIRPG, MDK_LRP1 and LGALS9_HAVCR2, CD74_COPA, C3_C3AR1, ANXA1_FPR3 interactions were upregulated in both ductal-tumor and malignant cells versus ductal-normal." (PMID 35087839, 2021). "When it comes to identifying by which precise molecular pathways LRP-1 plays its part on tumor progression and angiogenesis, the task is intricate." (PMID 34680548, 2021). "As LRP-1 is known to be upregulated by hypoxia, we ascertained that its expression was still low enough in our in vivo tumor model at the protocol end." (PMID 34680548, 2021). "In vitro, LRP-1 influences the tumor cells’ secretome which shapes EC behaviors among the microenvironment cells." (PMID 34680548, 2021). "A proteomics analysis revealed that LRP-1 supports tumor growth and angiogenesis by regulating TGF-β signaling and plasminogen/plasmin system." (PMID 34680548, 2021). "A proteomics analysis of TCM showed that LRP-1 supports angiogenesis and tumor growth through the TGF-β signaling and plasminogen/plasmin system modulation, among others." (PMID 34680548, 2021). "LRP-1 is also involved in cell migration, a key process in the acquisition of tumor cell invasiveness, by modulating integrin functions through a subtle control of their endocytosis/recycling cycle." (PMID 34680548, 2021). "A high expression level of LRP1 (ST) was significantly correlated with sex (p = 0.031), depth of tumor invasion (p = 0.024), high expression levels of αSMA (p < 0.001) and FAP (p = 0.001), and high numbers of infiltrating CD204+ macrophages (p = 0.001)." (PMID 33311557, 2021).
tumor (continued). "Due to its capacity to control pericellular levels of various growth factors and proteases, LRP-1 plays a crucial role in membrane proteome dynamics, which appears decisive for tumor progression." (PMID 34680548, 2021). "In vitro, HUVECs’ angiogenic potential was evaluated using a tumor secretome, subjected to a proteomic analysis to highlight LRP-1-dependant signaling pathways." (PMID 34680548, 2021). "We showed that LRP-1 repression in MDA-MB-231 tumors led to a significant tumor growth decrease (64%) compared to the control group." (PMID 34680548, 2021). "By means of an orthotopic mammary fat pad model, a Matrigel TM plug, and a CAMs assay, we showed that LRP-1 repression affects in vivo tumor growth by modulating, inter alia, angiogenesis." (PMID 34680548, 2021). "Through a proteomic approach, we demonstrated the extensive LRP-1’s influence on the MDA-MB-231 tumor cells’ secretome, where 962 proteins were identified." (PMID 34680548, 2021). "β1 integrin was indeed reported to promote the endocytic machinery of EGFR in cancer cells while LRP-1 was identified as a trigger for β1-integrin intracellular trafficking in the tumour context." (PMID 34831480, 2021). "The expression level of BAP31 was positively associated with the expression levels of SERPINE2, its downstream gene LRP1, and tumor cell proliferation marker Ki-67." (PMID 33363167, 2020). "In malignant diseases, the current trend seems to correlate LRP-1 overexpression with poor prognostic, increased cell proliferation, invasiveness and tumor recurrence." (PMID 32582700, 2020). "Regarding tumor growth and metastasis, the molecular contribution of LRP-1 remains misunderstood and be highly dependent of the tumor microenvironment." (PMID 32582700, 2020). "LRP1 was initially identified as a tumor suppressor controlling, by endocytic clearance, the extracellular matrix-degrading enzymes in the microenvironment of various invasive tumors." (PMID 32850302, 2020). "The role of LRP1 in cancer cell invasion and migration is, however, controversial as some of the findings demonstrated that low expression of LRP1 can also promote tumor cell progression." (PMID 32245111, 2020). "LRP1 is likely to be the most promising receptor because it constitutes an efficient drug carrier within tumor cells." (PMID 32850302, 2020). "LRP1 expression levels are often deregulated and reported to be related with advanced tumor stage and poor prognoses in several cancers, such as CRC, lung adenocarcinoma, melanoma, and hepatocellular carcinoma." (PMID 32245111, 2020). "In this tumor context, we provide evidence that LRP-1 promotes cell proliferation through regulating the levels of membrane DDR1 in 3D collagen matrices." (PMID 32582700, 2020). "LRP1 is a cell surface receptor that is widely expressed in many cells and can regulate tumor cell migration and cellular cholesterol homeostasis." (PMID 33203369, 2020). "By contrast, SerpinE2 and LRP1 were identified among the genes induced by ZEB-1, an EMT driver that limits the expression of LRP1-targeting miRNAs, thereby triggering tumor cell autocrine factors that predict poor survival in early stage of BC." (PMID 32850302, 2020). "LRP1 staining appeared intense in all stromal fibroblasts both outside and within the tumor tissue and scattered in macrophages and mast cells." (PMID 32850302, 2020). "In this tumor context, we provide evidence that LRP-1 regulates by endocytosis the cell surface levels of DDR1 expression." (PMID 32582700, 2020). "The proteomic signature of the stromal components of PDA identified the annexin A6/LDL receptor-related protein 1/thrombospondin 1 (ANXA6/LRP1/TSP1) as crucial for tumour cell crosstalk within the TME." (PMID 32942702, 2020). "The lysosomal localization of CD44 aptamers is supported by an earlier study as well, where LRP-1 protein facilitated lysosomal localization of CD44 receptor in tumor cells." (PMID 31080896, 2019).
tumor (continued). "Purified hrHsp90α protein in the absence of any carriers promotes cell migration by binding, activating and signalling through the LRP-1 cell surface receptor on both normal and tumour cells." (PMID 31641193, 2019). "In adenocarcinomas, IHC and LCM analyses highlighted the differential expression pattern of LRP1 between tumor and stromal cells." (PMID 29507659, 2018). "Conversely, our LCM analyses showed first that LRP1 was overexpressed in stromal cells when compared with tumor cells and second that LRP1 mRNA expression in tumor cells obtained by LCM were correlated to LRP1 IHC score on tumor cells." (PMID 29507659, 2018). "LRP1 expression levels are often dysregulated in cancer, while LRP1 role varies from one tumor type to another." (PMID 29507659, 2018). "Tumor IHC scores were not correlated with LRP1 mRNA expression levels of whole adenocarcinoma samples (p = 0.10; R2 = 0.02) but were correlated with LRP1 mRNA expression in tumor cells obtained after LCM (p = 0.003; R2 = 0.28)." (PMID 29507659, 2018). "These LRP1-mutated cases shared the same clinical and molecular profile as those with low LRP1 IHC score in tumor cells and low LRP1 mRNA expression: right location, MSI-H and CIMP-H." (PMID 29507659, 2018). "The value of LRP1 IHC score in tumor cells nearly reached statistical significance as a prognosis indicator of OS (p = 0.09) in multivariate analyses." (PMID 29507659, 2018). "Second, analysis of two independent patient cohorts revealed that low LRP1 expression correlated with right tumor location and specific molecular profile." (PMID 29507659, 2018). "In our study, low LRP1 IHC score in tumor cells was an indicator of poor OS and PFS in metastatic patients." (PMID 29507659, 2018). "On the contrary, high LRP1 expression was related to advanced tumor stages in endometrial carcinoma, breast cancer and prostate carcinomas." (PMID 29507659, 2018). "LRP1 not only regulates tumor invasion and migration through metalloproteinase MMP-2 and MMP-9 expression, but it also inhibits cell apoptosis by affecting caspase-313." (PMID 29138479, 2017). "The here first described ubiquitous expression of smLRP1 in tumour cell lines of different origins as well as human tissues extents our knowledge about LRP1." (PMID 28662213, 2017). "LRP1 was localized in tumor, stroma, and vascular cells, whereas CXCR3 was only detected in tumor cells and localized in the cytoplasm." (PMID 29146996, 2017). "With the purpose of establishing an integrated functional relationship between LRP-1-mediated endocytosis and cell-ECM interface, we here explored the ability of LRP-1 to bind cell surface integrins to regulate their uptake and recycling in tumor cells." (PMID 29108253, 2017). "As a consequence of its well-identified function in controlling extracellular proteolysis, LRP-1 was initially considered as preventing tumor aggressiveness." (PMID 29108253, 2017). "A shift in expression of smLRP1 relative to LRP1 towards smLRP1 was observed in most tumour cell lines compared to healthy tissue." (PMID 28662213, 2017). "We demonstrated that LRP1 is strongly expressed in the angiogenic part of the tumor, while it is decreased in the invasive part of the tumor." (PMID 29146996, 2017). "Calreticulin can interact with LDL-receptor-related protein 1 on macrophages and is required for the phagocytosis of tumor cell lines, whose function is to neutralize CD47–SIRPα interaction." (PMID 28484448, 2017). "We focused on CXCR3-A conformation and on the mechanisms controlling its activity and trafficking and investigated the role of CXCR3/LRP1 cross talk in tumor cell invasion." (PMID 29146996, 2017). "Concerning tumour biology LRP1 is controversially discussed, since it promotes and inhibits tumour development and progression depending on expression status." (PMID 28662213, 2017). "Superposition of LRP-1 and β1-integrin images revealed that both endogenous proteins partially colocalized in tumor cells." (PMID 29108253, 2017).
tumor (continued). "In order to comprehensively clarify the function of this endocytic receptor in tumor cells, others have sought to decipher LRP-1-related molecular mechanisms and signaling pathways." (PMID 29108253, 2017). "Comparing tumour cells and corresponding healthy tissues showed differences in expression of smLRP1 and LRP1." (PMID 28662213, 2017). "Assays were carried out in FTC-133 cells that remain a favored cellular model of LRP-1 study in the tumor context." (PMID 29108253, 2017). "Using a recently developed anti-smLRP1 antibody, the expression of the putative LRP1 protein isoform in tumour cell lines in Western blot and immunofluorescence staining was further investigated." (PMID 28662213, 2017). "Generally, there is a shift in expression of smLRP1 relative to LRP1 between tissues and tumour cells." (PMID 28662213, 2017). "Since both BBB and GBM exhibited high expression of LRP1, and with the deterioration of pathological degree, large amounts tumor cells with a higher density distribution of LRP1 were found in brain." (PMID 29182025, 2017). "In the invasive part of the tumor, LRP1 expression was completely shut down while CXCR3 was still present in tumor cells." (PMID 29146996, 2017). "Overall, deciphering the mechanisms of LRP-1-dependent endocytosis is key for increasing our knowledge on how β1-integrin expression, localization and traffic is regulated in tumor cells." (PMID 29108253, 2017). "LRP1 is widely expressed in several cell types including fibroblasts, neurons, astrocytes, macrophages, smooth muscle cells, and tumor cells." (PMID 29146996, 2017). "We believe that the ability of LRP-1 to mediate the uptake and recycling of β1-integrin has consequences on tumor progression beyond the regulation of cell adhesion, migration and invasion." (PMID 29108253, 2017). "In a tumor context, we here provide evidence that the LRP-1/β1-integrin complex constitutes an endocytic complex able to route β1-integrin to early endosomes, then to recycling Rab11-containing vesicles, while avoiding lysosome targeting." (PMID 29108253, 2017). "In a tumor context, we previously demonstrated that LRP-1 controls actin cytoskeleton organization and focal adhesion complex turnover." (PMID 29108253, 2017). "Despite these experimental and clinical data, the overall contribution of LRP-1 to tumor progression appears actually much more complex, remaining mostly misunderstood and somehow controversial." (PMID 29108253, 2017). "While CXCR3 is expressed in both, angiogenic and invasive areas, LRP1 expression is strongly reduced in invasive zones of the tumor." (PMID 29146996, 2017). "LRP-1, which exhibits both endocytosis and cell signaling properties, plays a key role in tumor invasion by regulating the activity of proteinases such as matrix metalloproteinases (MMPs)." (PMID 26903870, 2016). "LRP1-mediated phosphorylation of the extracellular signal-regulated kinase pathway and c-jun N-terminal kinase are also involved in tumor cell proliferation and invasion." (PMID 26738504, 2016). "The LRP1 expression increase by glia is not limited to MS, as previous work has demonstrated a similar pattern during CNS injury and neoplasia." (PMID 27400748, 2016). "A possibility is that LRP1 signaling activity both in the tumor cells, and potentially in cells in the environment, is altered." (PMID 27793045, 2016). "Together, these data suggest that miR-205 down-regulates LRP1 expression and its endocytic function and leads to suppressed tumor cell migration and invasion." (PMID 26738504, 2016). "LRP1 mediates the endocytosis of a diverse set of extracellular ligands that play important roles in tumor progression." (PMID 26738504, 2016). "Emerging in vitro and in vivo evidence demonstrates that LRP1 is critically involved in many processes that drive tumorigenesis and tumor progression." (PMID 26738504, 2016).
tumor (continued). "In human thyroid cancer cells, inhibiting LRP1 expression or increasing the level of uPA has been shown to enhance tumor cell invasion, specifically driving metastasis from lymph nodes and the lung." (PMID 26738504, 2016). "Recent work on data from tumor samples identified LRP1 as a hub in a biomarker network for multi-cancer clinical outcome prediction." (PMID 26617523, 2015). "This mini-review focuses on LRP1’s role in tumor growth and metastasis especially by modulation of the extracellular tumor environment." (PMID 26617523, 2015). "Initially, several groups reported decreased LRP1 expression levels in various cancer cell lines and tissues, thus assigning a tumor suppressive role to this receptor." (PMID 26617523, 2015). "Although highly challenging, developing strategies aiming at LRP1 targeting should be relevant in certain tumor microenvironments." (PMID 26617523, 2015). "They observed the failure of metastatic foci to grow in the lungs from xenografts of CL16 cells in SCID mice thus illustrating the relevance of LRP1 expression in tumor cells themselves." (PMID 26617523, 2015). "Post-translational regulation of LRP1 by proteolytic cleavage (also named shedding) is a critical mechanism in regulating cell-surface LRP1 expression, especially in tumor context." (PMID 26617523, 2015). "The secretion of chemokines by LRP1-deficient macrophages is enhanced (especially CCL3), resulting in an increased number of tumor-associated macrophages (TAM) in the tumor site." (PMID 26617523, 2015). "In some cancer types, LRP1 expression was correlated with invasiveness, tumor stage, and even clinical outcome." (PMID 26617523, 2015). "The authors provided evidence that the LRP1-deficient TAM collectively contribute to an increased VEGF amount into the tumor microenvironment, leading to increased tumor angiogenesis." (PMID 26617523, 2015). "Following upon a short general description of the structure and the function of LRP1, the present mini-review, however, focuses on the often indirect role of LRP1 in tumor growth and metastasis by modulation of the extracellular tumor environment." (PMID 26617523, 2015). "Clinically, both LRP1-SNRNP25 positive patients had tumor recurrence 21 months after surgery, and one of the patients developed lung metastases after 6 months." (PMID 25300797, 2014). "Several studies have reported that low expression of LRP1 is closely related to aggressive tumor cells and advanced tumor stages, such as human endometrial carcinoma, thyroid cancer, Wilms tumors, lung cancer, breast and prostate cancer." (PMID 22427881, 2012). "Low LRP1 expression was associated with poor HCC prognosis, with low expression independently related to shortened overall survival and increased tumor recurrence rate." (PMID 22427881, 2012). "Immunoreactivity of LRP1 protein was observed in in the cell membranes of tumor cells, stromal cells and peritumoral liver cells." (PMID 22427881, 2012). "Several lines of evidence indicate that this sequestration involved LRP1-mediated endocytosis of the Angiopep-2 conjugates into individual tumour cells." (PMID 22027709, 2011). "This broad distribution pattern in various cancers is consistent with increasing evidence that implicates LRP1 as a central player in oncogenesis, tumour progression, and metastasis." (PMID 22027709, 2011). "LRP-1 expression was also reported to be hypoxia-responsive and to support the metastatic dissemination of mouse tumor xenografts." (PMID 20644732, 2010). "The composition of talin-containing complexes was then analyzed in LRP-1-silenced cells compared to control tumor cells." (PMID 20644732, 2010). "Considering the lack of molecular knowledge about LRP-1 in the cancer field, we investigated the intracellular signaling network connecting LRP-1 to the aggressive behavior of tumor cells." (PMID 20644732, 2010).